FOXP3 (forkhead box P3)
Diseases named in the same sentence as FOXP3 in open-access papers (continued):
Sharing a sentence is not in itself a finding about the gene and the disease.
tumor (continued). "In addition, RP4 treatment affected the CRC-associated immune microenvironment in a tumor model by promoting cytotoxic CD8+ T and NKT (natural killer T) cells and inhibiting CD25+ Foxp3+ Treg cells." (PMID 36986805, 2023). "However, S15+ TAMs were spatially closer to CD4+FoxP3+ Tregs than S15− TAMs, and S15+ tumor cells in distinct ranges." (PMID 37674198, 2023). "Given that T cells in the localized tumor tissue as well as systemic peripheral blood play a pivotal and major role in regulation for anti-tumor immunity, we observed a trend of Foxp3/CD3 and Foxp3/CD8 ratios being higher in the high HLA-A expression group than in the low HLA-A expression group." (PMID 37382632, 2023). "Studies have confirmed that the immune components and functions of primary and metastatic renal cell carcinoma roughly overlap, however, the higher expression of PD-L1 and a lower CD8 to Foxp3 T cell ratio were found in metastatic lesions compared with matched primary tumor tissue." (PMID 37803307, 2023). "The significant difference in the number of CD4 + CD25 + FOXP3 + Tcells in the lymph node and tumor tissues was found in the population of the EPA and gp100 monotherapy groups compared to the combination therapy groups EPA + gp100 and Lip-EPA + Lip-gp100 (p < 0.0001)." (PMID 37037839, 2023). "Similarly tumors with an infiltrative pattern of invasion had higher tumor epithelial PD-1+ cells, and higher stromal FOXP3+ Tregs." (PMID 36368129, 2023). "The functional roles of tumour-FOXP3 are inconsistent and even reversed." (PMID 37868998, 2023). "In addition, FOXP3 was analyzed together with tumor infiltrating lymphocytes (TILs) to investigate the communication mechanism between FOXP3+ cells and effector T cells in TME." (PMID 36650632, 2023). "Additionally, we sought to investigate the relationship between CLDN18.2 and other factors, such as HER2, PD-L1, Foxp3, and tumour-infiltrating lymphocytes (TILs)." (PMID 37582713, 2023). "Furthermore, it has been noted that HPV+ neoplasms contain significantly higher densities of CD3+, CD4+, CD8+, CD20+ antigens and PD-1+ cells compared to HPV− tumours, with a trend towards the increased density of Foxp3+Treg cells." (PMID 36980527, 2023). "Hence, to evaluate if this occurred also in the patients treated with domatinostat, the ratio of CD8+ T cells to FoxP3+ Tregs in the tumor was examined using NanoString." (PMID 36920329, 2023). "FoxP3 was clearly stained in the nuclei of lymphocytes infiltrating the tumor tissue." (PMID 34319010, 2022). "Both ICOS+Foxp3+ Treg cells and pDCs in peripheral blood and tumor tissue could predict poor clinical outcome in GC patients." (PMID 35311157, 2022). "In vitro studies have shown that Foxp3 can act as a tumor suppressor gene." (PMID 35326661, 2022). "In addition, we found TIGIT expression in the tumor (r=-0.52, p=0.04) and FOXP3 in N1 ntbLNs (r=-0.56, p=0.03) to be correlated with TIDE scores." (PMID 35833140, 2022). "FoxP3 ablation contributed to reduced tumor invasiveness and immune escape in CCA." (PMID 36301031, 2022). "On the other hand, during another study on pancreatic ductal adenocarcinoma (PDAC), it was stated that exhaustion of myofibroblasts in this cancer leads to increased proliferation of CD4+ Foxp3+ Tregs in the tumor environment and inhibits the immune system in the tumor environment." (PMID 36275750, 2022). "In addition to abundant infiltrated lymphocytes, immunotherapy induced high levels of inhibitory components in post-treatment tissue samples, especially the FOXP3+ regulatory T cells in tumor and PD-L1 expression in the lymph node." (PMID 35173719, 2022).
tumor (continued). "Indeed, in the current study, FoxP3+ TILs were more accumulated in metastatic lymph nodes than in the primary tumour (P < 0.01, Wilcoxon rank-sum test)." (PMID 35597869, 2022). "However, the ratio between CD8+ and FoxP3+ cells within the tumor areas was higher in HPV-positive OPSCC." (PMID 36123711, 2022). "Among the clinicopathological and genomic characteristics, NMP exhibited the strongest negative correlation with DTICs, including CD3+ (P < 0.001), CD4+ (P = 0.065), CD8+ (P = 0.004), and FOXP3+ (P = 0.033) cells in the central tumor area (marked by a red arrow)." (PMID 35443723, 2022). "Understanding the correlation with FoxP3 and GzmB under different tumor conditions may prove to be important in the generation of tumor targeting therapies." (PMID 35326588, 2022). "However, the CD8+/FoxP3 frequency ratio was higher in tumor epithelia than in stroma indicating a higher influx of CD8+ cells than Tregs into tumor epithelia." (PMID 35634289, 2022). "We found that miR‐192‐5p/RB1 promoted the PDL1 expression on tumour cells and increased the percentage of PD‐1+FOXP3+ Tregs, which may enhance the immunosuppressive capacity of Tregs and promote immune evasion in GC." (PMID 35969010, 2022). "PD-1 improves FoxP3 expression and the suppressive function of induced Tregs in tumor tissues." (PMID 35455287, 2022). "Our results indicate that the infiltration of only one type of immune cell, such as CD4+ or FOXP3+ cells, might be sufficient for a suitable tumour microenvironment to prevent recurrence." (PMID 36253752, 2022). "More importantly, we observed enrichment of potentially exhausted and suppressive immune subsets in tumours: Foxp3+CD152+TIGIT+CD4+ regulatory T cells (Treg) (C4), PD1+CD103+CD45RO+CD8+ resident memory T cells (TRM) (C7) and PD1+ CD45RO+CD4+ memory T cells (C19)." (PMID 35301339, 2022). "FOXP3 expression may reflect direct suppression of malignant B cells by Tregs in cHL, or the suppression of tumor-supporting T cells in the microenvironment." (PMID 34980000, 2022). "Similar IHC results for Foxp3 were also seen for the xenograft and orthotopic tumour tissues." (PMID 35174623, 2022). "In breast cancer, the capacity of tumor-associated pDCs to produce type I IFN is substantially impaired, which in turn potentiates their capacity to promote the proliferation of tumor-associated forkhead box protein 3 (FOXP3)+ Treg cells." (PMID 35311157, 2022). "All tumors could be categorized into these patterns based on the combined mean CD8+, FOXP3+, and PD‐1+ densities in the tumor center and invasive front, and based on the ratio of combined density in tumor center/invasive front." (PMID 34743329, 2022). "Hence, researchers should try to block or activate the downstream target molecules of FOXP3 to intervene with tumor metastasis for clinical treatment." (PMID 36235242, 2022). "In addition, an increase in the density of FoxP3+ Tregs in the tumor tissue has been suggested to be a consequence of tumor-directed immune response, representing a contra regulatory response to the preexisting tumor immune aggression." (PMID 36551693, 2022). "Meanwhile, the tumour-derived factors may also mutually modulate the induction, migration, and immunosuppressive function of FOXP3+ Treg cells." (PMID 36569832, 2022). "Absent or mutation of Foxp3 will lead to severe autoimmunity in mice and significantly inhibit tumor growth." (PMID 35681736, 2022). "Immunohistochemistry for HLA class I expression was performed using HLA-ABC in tissue microarrays and was analyzed in relation to clinicopathologic characteristics of tumors and infiltration of CD4+, CD8+, and FOXP3+ tumor-infiltrating lymphocyte (TIL) subsets and PD-L1+ immune cells." (PMID 36437379, 2022).
tumor (continued). "However, a detailed tissue characterization that combined PD-1, PD-L1, CD8 and FOXP3 expression levels indicated the immune-mediated tumor growth and regression were only partially investigated in NSCLC." (PMID 35222387, 2022). "Therefore, in this review, we focus on the effects of FOXP3 on tumor metastasis and its relationship with TCM, which can provide evidence for further research and therapy in clinical settings." (PMID 36235242, 2022). "However, a few studies have shown a connection between the existence of Foxp3 + cells in the surrounding area of the tumor in colorectal cancer and a favorable survival." (PMID 36326418, 2022). "Similarly, the ratio of tumor-infiltrating FOXP3 (+)/CD8(+) T cells is associated with responsiveness to chemotherapy, suggesting an important role of T cells in tumor elimination." (PMID 36291171, 2022). "EZH2 inhibition, either pharmacologically or genetically, destabilizes FOXP3 expression in Treg cells and specifically reprograms tumour- infiltrating Treg cells through driving the expression pro-inflammatory genes (e.g., IL-2) while inhibiting key immunosuppressive genes such as IL-10 and TGF-β." (PMID 36569832, 2022). "FoxP3 is located in Treg and/or tumor cells and is one of the factors of poor prognosis of tumor." (PMID 35783156, 2022). "We further co-stained THBS2 with markers of cytotoxic T (CD8), Treg (FoxP3) and B (CD19) lymphocytes, as well as tumor-associated macrophages (CD68) 84 and nature killer (NK) cells (CD56) 85, which showed that immune cells were mainly located at the stromal compartment." (PMID 35547750, 2022). "Similar to sTILs, CD3+/FOXP3+ Treg cells were also evaluated in the three different tumour areas." (PMID 36552993, 2022). "These trends were validated by qRT-PCR analysis of FOXP3 gene expression in bulk tumor RNA." (PMID 35972798, 2022). "Meanwhile, the activity of EZH2 in Treg cells maintains the stability of FOXP3 protein, increases the number of tumor-infiltrating FOXP3+ Tregs, alters the homeostatic balance with tumor effector T cells in the microenvironment and impairs the anti-tumor immune response." (PMID 36713412, 2022). "A minority of HR+ BCs showed high levels of tumor-infiltrating FOXP3+ cells (38%; range, 35%–41%)." (PMID 35676750, 2022). "However, SI-2 treatment reduced the number of tumor-infiltrating CD4+/Foxp3+ regulatory T (Treg) cells compared to vehicle treatment." (PMID 36316775, 2022). "The tumour microenvironment (TME) in ALK rearranged cancers refers to the interplay of CD4 + T cells, CD8 + T cells, tumour associated macrophages (TAMs), mast cells and regulatory T cells (FOXP3 +)." (PMID 36591504, 2022). "In addition, the expression of PD-L1 inversely correlates with FOXP3 in tumor samples from CRC patients." (PMID 36614038, 2022). "This bsApt also induced an immune response (infiltration of CD3+ lymphocytes at tumor with increased expression of IFNγ, TNFα, and IL-10) and potentiated a combination of GVAX and transient Foxp3 blockade via the P60 peptide (resulting in decreased tumor size and increase survival) in vivo." (PMID 35141049, 2022). "Thus, we analysed expression of the FoxP3 gene as a functional marker of Treg cells and found a significant decrease in its expression in tumours of mice administered with targeted RGD4C.TPA.IL15IgK particles." (PMID 35758207, 2022). "Of note, FOXP3 was reported to promote tumor growth and metastasis by inducing EMT in NSCLC." (PMID 35688943, 2022). "Moreover, a high stroma expression of CD39 and CD73 results in significantly abundant FOXP3+ and PD-1+ tumor-infiltrating lymphocytes in tumors and hypoxia and acidity induce CD73 mRNA and protein levels in cancer cells." (PMID 36233088, 2022). "Current studies on the effect of FOXP3 on tumor metastasis in CRC also show contradictory results." (PMID 36235242, 2022).
tumor (continued). "Besides, the M2-like macrophages (F4/80+CD163+), MDSCs (CD11b+Gr-1+), and Tregs (CD3+CD4+FoxP3+) in the tumor regions were also analyzed by flow cytometry." (PMID 36319625, 2022). "Moreover, in agreement with B16F1 tumor profiling, the frequency of FoxP3+CD4+ Treg cells was comparable in YUMM3.3-βΑ and -Ctrl tumors." (PMID 35580932, 2022). "Therefore, 60% of CD4+ T cells in spleens of untreated non-tumor–bearing mice expressed FOXP3 as a marker for Tregs (p < 0.0001)." (PMID 35782876, 2022). "More recent studies by a retrospective cohort study suggest that the imbalance between cytotoxic and regulatory T lymphocytes(CD8+/Foxp3 T lymphocyte ratio) in the peri-tumoral PTC/HT(-) may affect the tumor-specific immune response." (PMID 35359359, 2022). "CD4+CD69+FOXP3− Tregs accounted for the vast majority of tumor‐infiltrating Tregs compared with FOXP3+ Tregs and could suppress the CD4+ T‐cell response mainly through mTGF‐β1." (PMID 35474948, 2022). "Moreover, FGL1 was positively associated with the CD3D expression and negatively associated with FOXP3, S100A9, and TPSB2 within the tumor site." (PMID 36268014, 2022). "In addition, a synthetic bacterial lipoprotein (a TLR1/TLR2 agonist) was reported to reduce the suppressive function of Foxp3+ Treg cells and enhance the cytotoxicity of tumor-specific CTL." (PMID 35309296, 2022). "Furthermore, the administration of glucomannan as a dietary supplement or adjuvant reduced regulatory T cell response through decreasing TGF-β and Foxp3 gene expression in the tumor microenvironment." (PMID 36298611, 2022). "Tumour-infiltrating FOXP3+ Treg cells may convert lactic acid to pyruvate, which is then converted into malic acid and citric acid that ultimately participates in the tricarboxylic acid cycle." (PMID 36569832, 2022). "It is noteworthy that tumours harbouring biallelic mutation in ARID1A showed the highest levels of CD3+ cells density (patients 2, 9 and 7), as well as of CD8+ (patients 2 and 7), and FOXP3+ (patients 2 and 7)." (PMID 36613564, 2022). "Therefore, it is important to investigate the balance between CD8+ TILs and FOXP3+ TILs in the tumor microenvironment." (PMID 35222387, 2022). "Here, we reveal novel findings that Rab37 mediates CHI3L1 secretion in T cells and macrophages, the major constituent cells in TME, to promote M2 macrophage polarization and higher FOXP3+ Tregs to CD8+ T cells ratio in the tumor region, ultimately establishing an immunosuppressive TME." (PMID 34987649, 2022). "Overall, high frequency of tumor-infiltrating FoxP3−Helios− T cells, and high frequencies of circulating FoxP3+, Helios+, FoxP3+Helios+, FoxP3+Helios−PD-1+, FoxP3+Helios+CTLA-4+, FoxP3+Helios−CTLA-4+ Tregs, and FoxP3−Helios+CTLA-4+ T cells, are associated with shorter DFS." (PMID 35655158, 2022). "It was reported that FOXP3 was highly expressed in the cytoplasm of PTC tumor cells." (PMID 36235242, 2022). "FoxP3 is a specific indicator of Treg cells and an essential inducer of immune escape to neoplasms." (PMID 36301031, 2022). "Interestingly, patients with high level of CD8+FoxP3+Helios−TIM-3+ in tumor tissue had significantly improved DFS." (PMID 35804964, 2022). "Moreover, although only small numbers of human Foxp3+ cells were detected in the tumor, ngTASO combined with anti-PD-1 antibody significantly reduced the number of intra-tumoral Foxp3+ cells." (PMID 36358638, 2022). "This indicated that FOXP3 could be considered a potential independent biomarker of tumor aggressiveness and metastasis." (PMID 36235242, 2022). "FOXP3 can also affect tumor metastasis by modulating chemokine responses in BC." (PMID 36235242, 2022). "Positive correlations were observed between levels of different immune checkpoint-expressing CD4+ T cells, including PD-1, TIM-3, LAG-3, and CTLA-4 with FoxP3+ Tregs, Helios+ T cells, FoxP3+Helios+ Tregs, and FoxP3+Helios− Tregs in the tumor microenvironment (TME)." (PMID 35455287, 2022).
tumor (continued). "Furthermore, we have studied the TIL Foxp3 infiltration level five-year DSS adjusted by the degree of stromal desmoplasia, tumor lymphocyte infiltration, nuclear polymorphism, and degree of tumor invasion." (PMID 35326661, 2022). "Recent studies suggest that FOXP3+ Treg cells may also play a functional role in tumour angiogenesis directly or indirectly to promote carcinogenesis." (PMID 36569832, 2022). "In addition, the neoantigen nanovaccine also upregulated the Treg subgroup (CD3+CD4+Foxp3+) and the expression of PD-L1 on tumor cells." (PMID 35418151, 2022). "Further functional studies are needed to understand whether the CD8+FOXP3+ T cells in the TME of FL have an “innate” anti‐tumor function or this is modulated by exposure to the immunochemotherapy treatment." (PMID 35451108, 2022). "Further, CD4+ T cells cultured in the presence of B7x+ tumor cells expressed Foxp3 at greater rates than those cultured with B7x- tumor cells, consistent with our in vivo findings, and this effect was diminished by the addition of anti-TGFβ1 blocking antibody into the culture." (PMID 35523809, 2022). "Additionally, we identified 4 distinct T lymphocytes subsets, of which cytotoxic CD8+ T cells predominated as effectors in tumor tissues, whereas tumor infiltrating FOXP3+ CD4+ regulatory T cells exhibited highly immunosuppressive characteristics." (PMID 35219893, 2022). "To investigate the immunogenicity of HR-d PDAC, we used multiplex immunohistochemistry (IHC) to compare the density and spatial distribution of CD8+ cytotoxic T-cells, FOXP3+ regulatory T-cells (Tregs), and CD68+ tumor-associated macrophages (TAMs) in HR-d versus HR/MMR-intact PDAC." (PMID 35547873, 2022). "In addition to Treg cells, previous studies revealed that Foxp3 is also expressed in various cancers and promotes tumor progression by activating cancer-specific cellular pathways, such as the Wnt/β-catenin signaling pathway and EMT." (PMID 36316775, 2022). "(2010) further demonstrated the cytolytic potential of CD4+ cyTreg in anti-tumor responses using two-photon microscopy in explanted tumor draining lymph nodes (LN) to show that DC death only occurred when perforin sufficient Foxp3+ Treg were present and in the presence of tumor antigens." (PMID 35493508, 2022). "We could demonstrate a direct correlation between the frequencies of CD8+ cells with CD163+ and/or FoxP3+ cells in single or combined tumor compartments (IM and/or TC) in the vast majority of patients’ tumors." (PMID 36551693, 2022). "First, tumor tissues had high levels of CD4+FOXP3+ Treg cells." (PMID 36483553, 2022). "Accordingly, any drug combinations that could reduce the levels of TGF-β, IL-10, and Foxp3 and increase the level of IFNγ, would have a potent inhibitory effect on tumor growth." (PMID 36544523, 2022). "FOXP3, for example, can inhibit tumor growth and induced apoptosis in HCC by targeting c-Myc." (PMID 36516498, 2022). "Furthermore, tumor-associated natural killer cells, B cells, and CD4 Foxp3-positive T cells were reported by two and myeloid-derived suppressor cells, granulocytes, mast cells, and leukocytes by one publication." (PMID 34845660, 2022). "Therefore, we assumed that the reason that Group A had more cases with positive PD‐L1 expression or positive CD4+ and FoxP3+ lymphocytes on tumor cell clusters was because of the immune reaction system occurred." (PMID 35137571, 2022). "They showed that LAYN was preferentially upregulated in tumor‐infiltrated FOXP3+Helios+ Tregs." (PMID 35474948, 2022). "Ample evidence has confirmed that FOXP3 is not only specifically expressed in Treg cells derived from the thymus or peripheral, but also abnormally expressed in a variety of tumor cells, and is closely related to the occurrence, development, and prognosis of tumors." (PMID 36522683, 2022).